PSAT1 (phosphoserine aminotransferase 1)
Description:
Involved in L-serine biosynthesis via the phosphorylated pathway, a three-step pathway converting the glycolytic intermediate 3-phospho-D-glycerate into L-serine. Catalyzes the second step, that is the pyridoxal 5'-phosphate-dependent transamination of 3-phosphohydroxypyruvate and L-glutamate to O-phosphoserine (OPS) and alpha-ketoglutarate. Acts as an inhibitor of ferroptosis in response to interferon-gamma (IFNG) by promoting GPX4 stability: following phosphorylation by CAMK2A, PSAT1 interacts with GPX4 and provides 2-oxoglutarate to EGLN3, leading to GPX4 hydroxylation and stability.
Synonyms: PSAT; PSA; EPIP; NLS2; PSATD
Tractability: Small molecule: a structure with a bound ligand is known; it has a high-quality binding pocket. PROTAC: ubiquitination databases record sites on it; its protein half-life has been measured.
Target class: Enzyme; Transferase
Gene: Protein-coding gene on chromosome 9 (78,297,094 to 78,330,098, forward strand). Ensembl gene ENSG00000135069.
Subcellular location (Human Protein Atlas): Cytosol
Pathways (Reactome):
Metabolism: Serine metabolism
Gene Ontology:
Molecular function: identical protein binding; O-phospho-L-serine:2-oxoglutarate aminotransferase activity; protein binding
Biological process: L-serine biosynthetic process; negative regulation of ferroptosis; pyridoxine biosynthetic process
Cellular component: cytosol; extracellular exosome
Genetic constraint (gnomAD): Loss-of-function variants: 40 observed, 39.89 expected, observed/expected ratio (o/e) 1, 90% interval 0.78 to 1.3. The upper end of that interval is the gene's LOEUF score, 1.3, which puts it in group 5 of 6, group 1 being the genes least tolerant of losing a copy. Missense variants: 400 observed, 457.36 expected, observed/expected ratio (o/e) 0.87, 90% interval 0.81 to 0.95. Synonymous variants: 146 observed, 172.71 expected, observed/expected ratio (o/e) 0.85, 90% interval 0.74 to 0.97.
Gene-disease validity (ClinGen):
ClinGen rates the evidence that PSAT1 causes each of these diseases.
neurometabolic disorder due to serine deficiency (autosomal recessive): Definitive. Serine-deficiency syndrome is a very rare infantile-onset potentially treatable neurometabolic disorder characterized clinically by microcephaly, neurodevelopmental disorders and seizures.
Homologues: Orthologues: chimpanzee PSAT1 (100% identical), dog PSAT1 (94% identical), rabbit PSAT1 (94% identical), guinea pig PSAT1 (92% identical), mouse Psat1 (92% identical), rat Psat1 (92% identical), pig PSAT1 (88% identical), tropical clawed frog psat1 (80% identical), zebrafish psat1 (75% identical), Drosophila melanogaster CG11899 (61% identical), Caenorhabditis elegans F26H9.5 (52% identical). Paralogues in human: AGXT (15% identical).
Diseases named in the same sentence as PSAT1 in open-access papers:
PSAT1 is named in the same sentence as 129 diseases in open-access papers, as found by Europe PMC text mining. Sharing a sentence is not in itself a finding about the gene and the disease. The quoted sentences say what the papers report.
breast carcinoma (64 papers, 2008 to 2025). "The overexpression of PHGDH and PSAT1 is significantly associated with poor clinical outcomes and malignant phenotypes in breast cancer." (PMID 39973065, 2025). "Increased transcription of PSAT1, caused by promoter hypomethylation, was also linked to a poor response to tamoxifen therapy and cancer recurrence in early-stage breast cancer." (PMID 38614981, 2024). "In contrast, lower levels of the mRNAs for Gdf15, Cdc25a, Ddit4 and Psat1 were associated with better prognosis in breast cancer patients." (PMID 34990474, 2022). "High levels of Klhl24, Hbp1, Crebrf, Ypel2, CD22 and Ypel3 were correlated with better outcomes, whereas lower levels of Gdf15, Cdc25a, Ddit4 and Psat1 were associated with better prognosis in breast cancer patients." (PMID 34990474, 2022). "In breast cancer, over-expression of PSAT1 was significantly associated with the malignant phenotype and survivals." (PMID 29297280, 2017). "High PSAT1 mRNA levels were associated in breast cancers with poor clinical response to endocrine therapy." (PMID 19671193, 2009). "It was also shown that high PSAT1 mRNA levels in breast cancer are associated with a poor clinical response to endocrine therapy." (PMID 18221502, 2008). "KLF9 over-expressing HEC-1-A cells had increased mRNA expression of BCAR3 and PSAT1, proteins previously implicated in the acquisition of tamoxifen resistance by breast cancer cells." (PMID 18783612, 2008). "In current research, PSAT1 has been identified as an oncogene associated with metastasis and poor prognosis in various malignancies, including lung cancer, liver cancer, colorectal cancer, breast cancer, ovarian cancer, and endometrial cancer." (PMID 40867682, 2025). "In current studies, PSAT1 has been identified as an oncogene associated with metastasis and poor prognosis in various malignancies, including lung cancer, liver cancer, colorectal cancer, breast cancer, ovarian cancer, and endometrial cancer." (PMID 40867682, 2025). "Additionally, increased expression of Psat1 in colorectal cancer and breast cancer is associated with a poor regression of tumor metastases following therapy." (PMID 20959002, 2010). "Moreover, Martens and colleagues reported that PSAT1 is overexpressed in some breast cancer samples and that this overexpression is associated with unfavorable clinical outcome in patients treated with the antiestrogen tamoxifen." (PMID 18221502, 2008). "Silencing PHGDH or PSAT1 in metastatic breast cancer cells inhibits their growth in the serine/glycine-limited condition, phenocopying the effects of NAT10 depletion." (PMID 40138393, 2025). "Collectively, these results showed that NAT10 and its downstream factors PHGDH/PSAT1 are crucial for the proliferation of metastatic breast cancer cells in the serine/glycine-limited environment." (PMID 40138393, 2025). "In breast cancer cells with LKB1 deficiency, there is an upregulation of PSAT1, PSPH, and serine hydroxymethyltransferase (SHMT1/2), all of which are involved in the de novo serine synthesis pathway (SSP)." (PMID 39973065, 2025). "We next interrogated the DNA methylation status of the PSAT1 promoter, as this was found to mediate silencing of this gene in ER/PR+ breast cancer." (PMID 40462988, 2025). "Consistent with our findings, several recent studies reported that high expression of NAT10, PHGDH, or PSAT1 is correlated with the poor survival in breast cancer, especially the TNBC." (PMID 40138393, 2025). "PHGDH and PSAT1 are essential enzymes for the glucose-derived serine/glycine biosynthesis pathway; using glucose, metastatic breast cancer cells synthesize serine/glycine to survive the amino acid–limited brain microenvironments." (PMID 40138393, 2025). "In contrast, PSAT1 overexpression upregulated the adhesion, migratory, and invasive abilities of breast cancer cells and increased the distant metastasis of tumors in a mouse model." (PMID 39199378, 2024).
breast carcinoma (continued). "To investigate the role of PSAT1 in breast cancer, we first analyzed its mRNA expression in breast cancer using the TCGA database." (PMID 39199378, 2024). "To explore the potential regulatory mechanism of PSAT1 in breast cancer, we knocked down or overexpressed PSAT1 by lentiviral transduction in the ER-negative breast cancer cell lines BT-549 and HCC1937." (PMID 39199378, 2024). "In conclusion, our study provides a new theoretical basis for the regulatory role of PSAT1 in tumors, which is of great significance for the individualized treatment of breast cancer." (PMID 39199378, 2024). "The results showed that PSAT1 expression was downregulated in breast cancer tissues compared to normal tissues." (PMID 39199378, 2024). "To validate the role of PSAT1 in controlling cancer metastasis in vivo, we generated 4T1 cells with stable knockdown or overexpression of PSAT1 (murine-derived breast cancer cell line)." (PMID 39199378, 2024). "According to previous reports, the high expression of PSAT1 in breast cancer can promote proliferation and metastasis." (PMID 39199378, 2024). "Emerging research has provided compelling evidence of PSAT1's crucial role in the initiation and advancement of distant metastasis in breast cancer." (PMID 38706897, 2024). "Here, we demonstrated that PSAT1 is significantly upregulated in ER-negative breast cancer cells and induces distant metastasis in breast cancer cells." (PMID 39199378, 2024). "Next, we evaluated PSAT1 expression in 360 breast cancer tissues to clarify the clinical significance of PSAT1 expression." (PMID 39199378, 2024). "In the present study, we identified differentially expressed genes, including ITGA2, by transcriptome sequencing of PSAT1-overexpressing breast cancer cell lines." (PMID 39199378, 2024). "A recent study found that PSAT1 also activates the Notch1/β-catenin signaling pathway to upregulate the metastatic ability of breast cancer and promote distant metastasis." (PMID 39199378, 2024). "Collectively, these results indicate that aberrant upregulation of PSAT1 is required for ER-related breast cancer cell metastasis." (PMID 39199378, 2024). "In this study, we found that PSAT1 is significantly highly expressed in ER-negative breast cancer and was able to promote breast cancer cell metastasis by regulating the ITGA2 protein." (PMID 39199378, 2024). "Recently, it has been reported that PSAT1 hypermethylation is related to T-cell dysfunction, shortened survival time and immune cell infiltration in breast cancer." (PMID 37147729, 2023). "TAZ/YAP can induce the expression of glutamate oxaloacetate transaminase 1 (GOT1) and PSAT1 to produce more α-ketoglutarate and to promote the growth of breast cancer cells." (PMID 37147729, 2023). "While PHGDH has traditionally been viewed as the rate-limiting step of serine biosynthesis, our data demonstrate that PSAT1 is limiting for serine biosynthesis in luminal breast cancer cells." (PMID 35045283, 2022). "For this study, we made use of several luminal and basal breast cancer cell lines, which we found to robustly maintain the differential PSAT1 expression phenotype that we observed in human breast tumors." (PMID 35045283, 2022). "We have found that luminal breast cancer cells are auxotrophic for serine because of lineage-specific hypermethylation of the PSAT1 gene and are sensitive to serine starvation both in vitro and in vivo." (PMID 35045283, 2022). "Accordingly, we studied the effect of methylation status of PSAT1 on survival prognoses in breast cancer and glioblastoma, and found that hypermethylation status was associated with better outcomes." (PMID 36105075, 2022). "Serine metabolism has also been suggested to play a role in the response of ER+ breast cancer cells to endocrine therapy, suggesting a potential role for PSAT1 in drug response." (PMID 35045283, 2022).
breast carcinoma (continued). "PSAT1 was found to be upregulated in ovarian cancer, breast cancer, and non-small cell lung cancer, enhancing cell proliferation, metastasis and chemical resistance, all of which result in poor prognosis." (PMID 35615948, 2022). "We also observed high PSAT1 gene methylation specifically in luminal breast cancer cell lines using CCLE data and our own methylation-specific PCR assay." (PMID 35045283, 2022). "Low PSAT1 prevents de novo serine biosynthesis and sensitizes luminal breast cancer cells to serine and glycine starvation in vitro and in vivo." (PMID 35045283, 2022). "On the other hand, we also discovered that primary tissues of breast cancer, liver cancer, clear cell renal cancer, and pancreatic cancer have lower levels of PSAT1 total protein expression." (PMID 36105075, 2022). "High PSAT1 expression has been detected in non-small cell lung cancer, breast cancer, and esophageal squamous cell carcinoma, and PSAT1 expression can enhance tumorigenesis and metastasis 22-24." (PMID 34405023, 2021). "Currently, PSAT1 has mainly been explored in non‐small‐cell lung cancer, colon cancer, esophageal cancer, and breast cancer." (PMID 33763366, 2021). "Upon siRNA‐mediated knockdown of IKKε, downregulation of PSAT1 at the transcriptional level was observed in 5 out of 9 breast cancer cell lines tested (ZR‐75‐1, T47D, MDA‐MB‐468, Cal120 and HCC1143)." (PMID 32783398, 2020). "We show a positive correlation between IKKε expression, immune cell infiltration and the expression of the serine biosynthesis pathway enzyme PSAT1 in human breast cancer tissues and in the METABRIC breast cancer dataset." (PMID 31930708, 2020). "High PSAT1 expression correlates with poor prognosis in many tumors including breast cancer, colorectal, nasopharyngeal, and esophageal carcinomas and is linked to drug resistance." (PMID 32762776, 2020). "We found that the promoter regions of PSAT1 and PHGDH contain binding sites for MYC-controlled activating transcription factor 4 (ATF4), which was reported to regulate PSAT1 expression in breast cancer." (PMID 32138178, 2020). "PSAT1 was regarded as a poor prognostic marker in non-small cell lung cancer, esophageal squamous cell carcinoma, breast cancer and colorectal cancer and contributes to cancer cell proliferation and metastasis." (PMID 31861486, 2019). "The expression level of PSAT1 in breast cancer tissues and cells was analyzed using real-time-PCR (RT-PCR), TCGA datasets or immunohistochemistry (IHC)." (PMID 29216929, 2017). "Among these genes, the gene PSAT1 had been well studied in several cancers, such as the breast cancer, the lung cancer and the esophageal squamous cell carcinoma." (PMID 29297280, 2017). "The knockdown of PSAT1 significantly suppressed the viability of these two breast cancer cell lines compared with control cells." (PMID 29216929, 2017). "We found that PSAT1 expression was significantly down-regulated in breast cancers compared with normal tissues." (PMID 29216929, 2017). "To investigate the potential role of PSAT1 in breast cancer, we first analyzed PSAT1 mRNA expression in breast cancer RNAseq data from the TCGA." (PMID 29216929, 2017). "We found that PSAT1 regulates the expression of cyclin D1, which is an important regulator of G1 to S phase in a variety of cancers, including breast cancer, to promote cell cycle progression." (PMID 29216929, 2017). "A cohort of ER positive, hormonal therapy naïve primary breast carcinomas was immunohistochemically (IHC) stained for PSAT1." (PMID 28522855, 2017). "Here, we show that, mechanistically, NAT10 regulates 3-phosphoglycerate dehydrogenase (PHGDH) and phosphoserine aminotransferase 1 (PSAT1) via its RNA helicase domain to support the proliferation of metastatic breast cancer cells in the serine/glycine-limited brain microenvironment." (PMID 40138393, 2025).
breast carcinoma (continued). "However, like ER/PR+ breast cancer, SA in AML was remarkably and consistently associated with PSAT1 suppression, and its re-expression provided rescue of SA in multiple AML cell lines." (PMID 40462988, 2025). "Phosphoserine aminotransferase 1 (PSAT1) catalyzes the second step of the serine-glycine biosynthesis pathway, and its overexpression was reported in ovarian cancer, lung adenocarcinoma, and breast cancer." (PMID 39596687, 2024). "Mechanistically, PSAT1 facilitated breast cancer metastasis via the p-AKT/SP1/ITGA2 axis." (PMID 39199378, 2024). "Therefore, we suggest that PSAT1 affects breast cancer metastasis by regulating the expression of ITGA2." (PMID 39199378, 2024). "We wondered whether PSAT1 is capable of broadly activating key proteins affecting malignant tumor function through phosphorylation and, ultimately, promoting breast cancer metastasis." (PMID 39199378, 2024). "PSAT1 could increase distant breast cancer metastasis through upregulation of the p-AKT/SP1/ITGA2 axis." (PMID 39199378, 2024). "Abundant evidence indicated that PSAT1 could promote metastasis of lung adenocarcinoma, enhance cell proliferation in breast cancer, contribute to cell growth and cisplatin resistance in cervical cancer." (PMID 39392257, 2024). "Interestingly, tamoxifen‐resistant MCF7 breast cancer cells have been shown to restore sensitivity to anticancer drugs via the YAP/TAZ–recombinant phosphoserine aminotransferase 1 (PSAT1) axis." (PMID 37576865, 2023). "In addition, HIF-1 and HIF-2 transcription factors can induce the expression of PHGDH, PSAT1, and SHMTs in breast cancer cell lines under hypoxia." (PMID 37147729, 2023). "High expression of PSAT1 has been suggested to regulate serine anabolism, promotes osteoclast differentiation and enhances their activity, regulates the tumor microenvironment, and thus promotes bone metastasis in breast cancer." (PMID 36061202, 2022). "This also reflects that our research results are inconsistent with the previous results, which may be due to different mechanism of PSAT1 in different pathological types of breast cancer." (PMID 36105075, 2022). "This suggested that DNA methylation may be the most relevant suppressive mechanism of PSAT1 expression in luminal breast cancer cells." (PMID 35045283, 2022). "The results revealed that PSAT1 expression was varied in different stages of breast cancer." (PMID 36105075, 2022). "It is preliminarily concluded that PSAT1 may play an immune related role in lung cancer and breast cancer, and has certain predictability for the efficacy of immunotherapy." (PMID 36105075, 2022). "Interestingly, our results showed that PSAT1 first increased and then decreased with the increase of breast cancer stage, and its expression in breast cancer was lower than that in normal tissues." (PMID 36105075, 2022). "Using data from the Cancer Cell Line Encyclopedia (CCLE) and our own qPCR and western blots, we found that breast cancer cell lines robustly maintain the low-PSAT1 phenotype of luminal tumors, while the differences in PHGDH and PSPH were less pronounced or absent." (PMID 35045283, 2022). "This suggests that elevated PSAT1 in the early stage of breast cancer may be one of the markers for metastasis." (PMID 36105075, 2022). "PSAT1 may be a new biomarker for predicting the efficacy of immunotherapy for lung cancer and breast cancer." (PMID 36105075, 2022). "Hence, the prognostic significance of PSAT1 needs to be dynamically evaluated at different stages of breast cancer." (PMID 36105075, 2022). "While this limitation of our breast cancer cell line models may simplify our mechanistic understanding of luminal serine auxotrophy, low PSAT1 and low PHGDH would likely result in an even stronger serine auxotrophy phenotype in human breast tumors." (PMID 35045283, 2022).